VGLL4 (vestigial like family member 4)
Diseases named in the same sentence as VGLL4 in open-access papers (continued):
Sharing a sentence is not in itself a finding about the gene and the disease.
breast tumor (2 papers, 2017 to 2020). "Hypoxic stress, which is a frequently observed characteristic in tumor, caused alternative splicing of VGLL4 gene in human breast tumor cells, and this alternative splicing was suggested to affect its tumor-suppressing role." (PMID 32793503, 2020). "Taken together, our data demonstrate that VGLL4 suppresses aberrant proliferation in breast tumors by selective inhibition of the YAP onco-protein." (PMID 28733631, 2017). "VGLL4 repressed the proliferation of breast tumor cells via the inhibition of YAP-mediated gene induction, and high expression of VGLL4 correlated with poor prognosis of breast tumor patients." (PMID 32793503, 2020).
colon cancer (2 papers, 2017 to 2024). "Another YAP-transcriptional suppressor, Vestigial-like-4 (VGLL-4), has also recently emerged as a novel tumour suppressor in colon cancer by regulating both the YAP/TAZ and β-catenin-TCF4 complex." (PMID 38927266, 2024). "Altogether, these observations indicate that VGLL4 suppresses proliferation of colon cancer cells." (PMID 28051067, 2017).
heart failure (2 papers, 2022 to 2024). Inability of the heart to pump blood at an adequate rate to meet tissue metabolic requirements. "In our previous study, we showed that high-dose AAV.VGLL4K225R-mediated precautious activating VGLL4 in the neonatal heart caused heart failure, and the CMs of these failure hearts underwent pathological hypertrophic growth." (PMID 39195232, 2024). "We previously showed that the activation of VGLL4 in the postnatal heart decreased CM proliferation and caused heart failure." (PMID 36139407, 2022). "Overexpressing a K225R-mutated VGLL4 in the neonatal heart disrupted the TEAD/YAP interaction and caused cardiac hypoplasia and heart failure." (PMID 36139407, 2022). "We previously found that the primary interaction partner of TEAD1 is YAP in the neonatal heart and that overexpressing a K225R-mutated VGLL4 in the neonatal heart disrupted the TEAD1–YAP interaction, suppressed CM proliferation, and caused heart failure." (PMID 36139407, 2022). "In line with the biochemistry findings, AAV.cTnT.VGLL4 did not affect postnatal heart growth, while AAV.cTnT.VGLL4K225R (AAV.VGLL4K225R) caused heart failure." (PMID 39195232, 2024).
lymph node metastasis (2 papers, 2017 to 2025). "Lower levels of VGLL4 also correlate with adverse clinical parameters such as tumor size and lymph node metastasis." (PMID 39857952, 2025). "Moreover, VGLL4 staining was significantly associated with tumour size, lymph node metastasis and TNM stage (P<0.05), but not significantly correlated to age, gender and tumour metastasis." (PMID 28051067, 2017).
prostate carcinoma (2 papers, 2019 to 2021). A carcinoma that arises from epithelial cells of the prostate gland. "In conclusion, LINC00641 can be used as a tumor suppressor of prostate cancer, which can increase the expression of VGLL4 and inhibit the proliferation and invasion of prostate cancer cells by competitively binding miR-365a-3p through the ceRNA mechanism." (PMID 35155216, 2021). "Then it was found that VGLL4, as the downstream target gene of miR-365a-3p, was down regulated in prostate cancer and negatively correlated with miR-365a-3p." (PMID 35155216, 2021).
acne (1 paper, 2024). An inflammatory process of the sebaceous glands which is characterized by comedones, nodules, papules and/or pustules on the skin. "Our research, through colocalization analysis, has identified genes such as HRH1, ATG7, and VGLL4 as related to the risk of acne, but currently, the clinical applications of these genes or proteins are mainly still in the research phase." (PMID 39297226, 2024). "Our analysis also spotlighted several other genes implicated in acne risk, including HRH1, ATG7, and VGLL4." (PMID 39297226, 2024).
aortic stenosis (1 paper, 2019). Aortic valve stenosis is a aortic valve disease caused by the incomplete opening of the aortic valve. "Besides, ejection fraction (EF), fractional shortening (FS) were increased in Vgll4-/- hearts, suggesting that Vgll4-/- hearts developed aortic stenosis and undergo compensatory hypertrophy, a feature of hypercontractile state." (PMID 30789911, 2019).
asthma (1 paper, 2020). "The hypermethylated genes have roles in asthma (VGLL4, AGR2), neurologic development (AGAP1, OTX2), and immune regulation (SCAMP5, SLC11A1)." (PMID 32850550, 2020). "Down-regulation of VGLL4 due to hypermethylation after exposure to HCA could lead to dysregulation of Wnt/β-catenin signaling, abnormal lung development, and an increased risk for asthma." (PMID 32850550, 2020).
atrioventricular septal defect (1 paper, 2019). "Interestingly, VGLL4 is located within the CHD sensitive region of 3p25 deletion syndrome which is frequently related to atrioventricular septal defect (AVSD) (OMIM: 613792), highlighting its role in valvulogenesis." (PMID 31799250, 2019).
cervical cancer (1 paper, 2017). A primary or metastatic malignant neoplasm involving the cervix. "Similar results were also obtained in HeLa cervical cancer cells although to a lesser degree where VGLL4-003 was upregulated by 1.5-fold and VGLL4-001 was downregulated by 1.5-fold." (PMID 28642487, 2017).
cholangiocarcinoma (1 paper, 2022). A carcinoma that arises from the intrahepatic biliary tree (intrahepatic cholangiocarcinoma) or from the junction, or adjacent to the junction, of the right and left hepatic ducts (hilar cholangiocarcinoma). "We found that loss of Vgll4 completely rescued the developmental defects of Yap mutant livers and lungs, greatly enhanced Nf2 mutant liver intrahepatic cholangiocarcinoma development, and ameliorated CCl4-induced liver injury." (PMID 36522128, 2022). "The physiological importance of this dual mechanism is supported by our findings that loss of Vgll4 dramatically enhanced intrahepatic cholangiocarcinoma formation in Nf2-deficient livers." (PMID 36522128, 2022).
Cirrhosis (1 paper, 2018). A chronic disorder of the liver in which liver tissue becomes scarred and is partially replaced by regenerative nodules and fibrotic tissue resulting in loss of liver function. "However, AFP, cirrhosis and Child-Pugh system were not correlated with 5-HT and YAP/VGLL4 ratio." (PMID 29950605, 2018).
colitis (1 paper, 2026). Inflammation of the colon. "Consistently, public datasets of human colitis show reduced VGLL4 expression." (PMID 41629625, 2026). "VGLL4 expression is downregulated in response to irradiation and DSS-induced colitis." (PMID 41629625, 2026).
head and neck squamous cell carcinoma (1 paper, 2025). A squamous cell carcinoma that arises from any of the following anatomic sites: lip and oral cavity, nasal cavity, paranasal sinuses, pharynx, larynx, and salivary glands. "In head and neck cancer, this Hippo-Wnt crosstalk is particularly critical; downregulation of VGLL4 is common in certain head and neck squamous cell carcinomas, leading to the co-activation of YAP/TAZ and β-catenin, which in turn promotes cancer cell proliferation and invasion." (PMID 40486910, 2025).
intestinal cancer (1 paper, 2017). "We then chose adenomatous polyposis coli (APC) mutant mice (APCmin/+), a well-known mouse model for colorectal and intestinal cancer, to further corroborate the function of VGLL4 in CRC." (PMID 28051067, 2017).
liver fibrosis (1 paper, 2022). "In comparison, age-matched littermates with liver-specific Vgll4 knockout subjected to the same treatment regime exhibited much lower levels of liver fibrosis and apoptosis at all time points." (PMID 36522128, 2022).
mesothelioma (1 paper, 2024). A usually malignant and aggressive neoplasm of the mesothelium which is often associated with exposure to asbestos. "To validate our whole-genome screens, we used CRISPR/Cas9 mutagenesis with two independent sgRNAs to mutate NF1, SOCS3, and VGLL4 in H226 and H2052 cells, as well as a third mesothelioma cell line, MSTO-211H, which harbors inactivating mutations in both LATS1 and LATS2." (PMID 39103676, 2024). "VGLL4 loss conferred strong resistance to VT107, suggesting that VT107 induces transcription repression by VGLL4/TEAD and associated transcription co-repressors and this is important for VT107’s ability to limit mesothelioma cell proliferation and viability." (PMID 39103676, 2024).
pancreatic adenocarcinoma (1 paper, 2025). "VGLL4 levels in cancer cells are typically lower compared to normal tissues, and reduced expression of VGLL4 is often associated with poor survival outcomes in numerous cancers, including lung, gastric, breast, colorectal, bladder, pancreatic adenocarcinoma, and esophageal squamous cancer." (PMID 39857952, 2025).
pulmonary hypertension (1 paper, 2023). Increased pressure within the pulmonary circulation due to lung or heart disorder. "In addition, VGLL4 promotes pulmonary hypertension and pulmonary arterial remodeling through a signal transducer and the activation of transcription 3 (STAT3) signaling; alternatively, the specific knockout of VGLL4 in ECs increases the YAP expression and heart valve malformation." (PMID 36675179, 2023).
tumor (67 papers, 2014 to 2026). "In GC, there was a gradual increase of approximately three-fold in the ratio of YAP1-to-VGLL4 protein expression from GC grade I to grade IV, and their mRNA ratio was closely associated with aggressive tumor features." (PMID 36289774, 2022). "The IHC results from the tumors showed that VGLL4 expression was significantly higher in the VGLL4 overexpression group than in the NC group, indicating that VGLL4 overexpression may be the cause of inhibition of tumor growth in vivo in mice." (PMID 31748508, 2019). "The results showed that VGLL4 mRNA expression was associated with tumor size and Ki67 expression." (PMID 31748508, 2019). "Furthermore, 5-HT level, YAP/VGLL4 ratio and tumor size were proved as independent risk factors of HCC patients in our study." (PMID 29950605, 2018). "High expression of miR-454 may be one of the causes of the downregulation of VGLL4 in TNBC, and VGLL4 acts as a tumor suppressor in TNBC by interacting with STAT3 and subsequently suppresses the STAT3 signaling axis, providing potential biomarkers and therapeutic approaches for this fatal disease." (PMID 31748508, 2019). "VGLL4, a known prognostic marker and tumor suppressor, showed decreased expression in the lamina propria during late CRC stages, suggesting that its downregulation correlates with the tumor progression beyond mucosa." (PMID 39857952, 2025). "Due to its negative regulation of pathways involved in tumor proliferation, the VGLL4 acts as a tumor suppressor." (PMID 39857952, 2025). "This aligns with studies demonstrating that VGLL4 overexpression inhibits cancer cell proliferation and migration, suggesting its function as a tumor suppressor." (PMID 39857952, 2025). "USP11 functions as a tumor suppressor by stabilizing VGLL4 in a YAP-dependent manner, which inhibits cancer cell growth, migration, and invasion." (PMID 38722330, 2024). "The trend of linear decrease in the expression of VGLL4 was observed with the progression of tumor grade (p < 0.0001)." (PMID 38255254, 2024). "The trend of linear decrease in the expression of VGLL4 was observed with the progression of tumor grade." (PMID 38255254, 2024). "USP11 controls its stability by promoting deubiquitination of a residual protein (VGLL, a tumor suppressor) and exerts its tumor suppressor effect through the VGLL4/YAP-TEAD regulatory ring." (PMID 39185411, 2024). "Therapeutically, blocking the YAP-TEAD interaction by the use of a peptide mimicking the role of VGLL4, suppressed tumor growth in xenograft and carcinogen-induced murine GC models." (PMID 36635265, 2023). "The mRNA levels of VGLL4 are downregulated in a significant fraction of GC cases and are inversely correlated with tumor stage and lymph node metastasis." (PMID 36635265, 2023). "VGLL4, a vestigial-like protein 4, is also found to be a tumour suppressor in human cancers via direct competition with YAP for binding TEADs." (PMID 36759723, 2023). "The reciprocal, compensatory increase of VGLL4 or Hippo pathway tumor suppressors when the other mechanism is disabled further supports the central importance of the dual mechanisms in Hippo pathway regulation." (PMID 36522128, 2022). "Recent studies demonstrated that VGLL4 exhibited tumor-suppressive roles in many cancer types, a process mainly depends on its competition with YAP1 for binding to TEAD." (PMID 36289774, 2022). "Recently, verteporfin and VGLL4 mimetic peptides have been shown to inhibit YAP/TAZ-dependent transcription as well as suppress tumor growth." (PMID 35054341, 2022). "VGLL4 can inhibit cell proliferation and tumor growth in HCC, which was attributable to an arrest of the G2/M phase and apoptosis promotion by adenovirus." (PMID 36408192, 2022). "Vestigial Like Family Member 4 (VGLL4) is a tumor suppressor that competes with YAP in binding to TEADs, and thus, inhibits the transcriptional activity of YAP." (PMID 35453784, 2022).
tumor (continued). "In contrast to other VGLL family members, VGLL4 works as a novel tumor suppressor through cooperating with TEAD transcription factors." (PMID 34831362, 2021). "Vestigial Like Family Member 4 (VGLL4) is a gene related to Wnt/β-catenin signaling pathway regulation, cell cycle regulation, and immune regulation via T-cell mediated tumor regression." (PMID 32850550, 2020). "The tumor-suppressing role of VGLL4 was first observed in the transposon Sleeping Beauty-mediated mutagenesis in murine Kras-driven pancreatic adenocarcinoma models." (PMID 32793503, 2020). "VGLL4 expression has been observed in a wide range of tissues, and hence, it is likely to be a ubiquitously expressed tumor suppressor." (PMID 32793503, 2020). "IRF2BP2 stabilized VGLL4 protein and repressed tumor progression via the inactivation of YAP-TEAD4 complex in liver cancer." (PMID 32793503, 2020). "In contrast, down-regulation of VGLL4 was detected in various tumors, and the tumor-suppressing role of VGLL4 has been demonstrated." (PMID 32793503, 2020). "It has also been reported that IRF2BP2 and VGLL4 promote tumor growth through the induction of the immune checkpoint protein programmed cell death-ligand 1 (PD-L1) and immune evasion of tumor cells." (PMID 32793503, 2020). "By silencing and overexpressing VGLL4, we demonstrated that VGLL4 is a critical tumor suppressor of TNBC cells." (PMID 31748508, 2019). "The expression of VGLL4 protein in xenograft tumour tissues from miR‐301b‐3p knockdown group was significantly higher than that in control group (P < 0.05)." (PMID 31207037, 2019). "VGLL4 is recognized as a novel direct target of miR‐301b‐3p and participates in miR‐301b‐3p‐induced tumour progression of HCC." (PMID 31207037, 2019). "In summary, these findings support the conclusion that VGLL4 serves as a tumor suppressor in TNBC in vitro and vivo." (PMID 31748508, 2019). "qRT‐PCR analysis revealed that the expression of VGLL4 mRNA was down‐regulated in HCC compared to matched tumour‐adjacent tissues (P < 0.0001)." (PMID 31207037, 2019). "Vestigial-like 4 (VGLL4) is a tumor suppressor that competitively binds to TEAD via its tondu domain (TDU), thereby preventing YAP from mediating transcription." (PMID 31018586, 2019). "It had been explored that VGLL4 has a tumor suppressor efficacy in lung, gastric, colorectal, and breast cancer." (PMID 31781493, 2019). "IHC staining suggested that VGLL4 expression in tumor sections from the VGLL4 overexpression group was significantly higher than that in tumor sections from the NC group." (PMID 31748508, 2019). "Through the analysis of clinical database, 5-HT level was found to be associated with PLT, tumor size, death and YAP/VGLL4 ratio and YAP/VGLL4 ratio was correlated with ALP, GGT, tumor size, vascular invasion, death and the 5-HT level." (PMID 29950605, 2018). "Accumulating studies have reported that YAP and VGLL4 function as regulators in tumor playing opposite effects via competitive inhibition." (PMID 29950605, 2018). "Multivariate analysis demonstrated that only tumor size, 5-HT level and YAP/VGLL4 ratio were associated with overall survival and recurrence-free survival synchronously." (PMID 29950605, 2018). "VGLL4, a novel tumor suppressor, is reported to compete with YAP for pairing with TEADs to disrupt the YAP-TEADs complex formation." (PMID 29950605, 2018). "The results suggest that VGLL4 is a candidate tumor suppressor gene which acts by selectively antagonizing YAP-dependent tumor growth." (PMID 28733631, 2017). "Taken together, these observations indicate that VGLL4 suppresses CRC tumour growth at least partially by inhibiting the Wnt/β-catenin pathway." (PMID 28051067, 2017). "We found that the messenger RNA (mRNA) levels of VGLL4 were negatively correlated with tumour stage." (PMID 28051067, 2017). "VGLL4 (Vestigial-Like Family Member 4) is a transcriptional cofactor which functions as a tumor suppressor in multiple cancers." (PMID 28642487, 2017).